BMP6 (bone morphogenetic protein 6)
Diseases named in the same sentence as BMP6 in open-access papers (continued):
Sharing a sentence is not in itself a finding about the gene and the disease.
autoimmune disease (1 paper, 2020). A disorder resulting from loss of function or tissue destruction of an organ or multiple organs, arising from humoral or cellular immune responses of the individual to their own tissue constituents. "Using cell culture and mouse models of SS, we studied whether targeted pharmacological blockade of BMP6 signaling might attenuate autoimmune disease activity." (PMID 32076051, 2020).
Brain atrophy (1 paper, 2025). Partial or complete wasting (loss) of brain tissue that was once present. "To fill this gap, we aimed to investigate the association between plasma BMP6 levels and six MRI-based regional brain atrophy, including hippocampus, entorhinal cortex, fusiform gyrus, middle temporal gyrus, ventricles, and whole brain." (PMID 40734820, 2025). "A series of linear mixed-effects models were built to examine the associations of plasma BMP6 levels with brain atrophy over time." (PMID 40734820, 2025). "However, few studies have examined the association between plasma BMP6 levels and brain atrophy in older adults." (PMID 40734820, 2025). "Second, association of CSF BMP6 levels and brain atrophy remains to be fully elucidated." (PMID 40734820, 2025). "Finally, the observational nature of our study precludes causal inferences; further interventional studies are necessary to establish a causal relationship between BMP6 levels and brain atrophy." (PMID 40734820, 2025). "Associations of plasma BMP6 with the rates of regional brain atrophy." (PMID 40734820, 2025). "For instance, pharmacological agents that increase BMP6 activity or mimic its effects could potentially slow down the rate of brain atrophy and neurodegeneration." (PMID 40734820, 2025). "However, few studies have investigated the relationship between plasma BMP6 levels and brain atrophy in living humans." (PMID 40734820, 2025). "However, the lack of association between BMP6 levels and ventricle size suggests that the influence of BMP6 is likely targeted to specific regions rather than being a broad indicator of brain atrophy." (PMID 40734820, 2025). "However, the relationship between plasma BMP6 levels and brain atrophy, as measured by MRI, has not been previously explored." (PMID 40734820, 2025).
Burkitt lymphoma (1 paper, 2005). A rare form of malignant mature B-cell non-Hodgkin lymphoma. "The BMP-6-induced inhibition of proliferation was dose-dependent in both peripheral B cells and the Burkitt lymphoma cell line Ramos (40% reduction of DNA synthesis)." (PMID 15877825, 2005). "Additionally, BMP-6 induced cell death in CD27+ memory B cells as well as in a Burkitt lymphoma cell line (Ramos)." (PMID 15877825, 2005).
cardiomyopathies (1 paper, 2022). "Our data suggested similar dysregulation of these molecular pathways in adult-onset cardiomyopathies with increased BMP6 and NRG1 in EC7 and decreased INHBA." (PMID 35926050, 2022).
cerebral cavernous malformation (1 paper, 2021). A disorder characterized by malformations in the structure of the capillaries in the brain. "Increased BMP6 or BMP2 expression have also been demonstrated in cerebral cavernous malformations and cancer." (PMID 33021694, 2021). "As BMP6 upregulation has also been shown to mediate onset and progression of cerebral cavernous malformations by inducing BMP and TGFβ-signaling, Hippo pathway inhibitors may act as potential molecular targets for this disease." (PMID 33021694, 2021).
chronic heart failure (1 paper, 2022). "In patients with chronic heart failure, levels of BMP6 were elevated compared to controls, with higher levels in patients of more advanced disease." (PMID 36574434, 2022).
chronic obstructive pulmonary disease (1 paper, 2022). A chronic and progressive lung disorder characterized by the loss of elasticity of the bronchial tree and the air sacs, destruction of the air sacs wall, thickening of the bronchial wall, and mucous accumulation in the bronchial tree. "From the GWAS Catalog, we found that BMP6 was associated with FVC; FEV1; and, to a lesser extent, chronic obstructive pulmonary disease and small cell lung carcinoma." (PMID 35624665, 2022).
Cirrhosis (1 paper, 2024). A chronic disorder of the liver in which liver tissue becomes scarred and is partially replaced by regenerative nodules and fibrotic tissue resulting in loss of liver function. "BMP6 levels did not change with cirrhosis, excluding the role of BMP6 for the altered levels of these iron parameters in cirrhosis." (PMID 39200147, 2024). "A total of 19 septic patients and nine patients with SIRS suffered from liver cirrhosis; however, this pathology did not affect plasma BMP6 levels compared to the plasma levels of patients without cirrhosis." (PMID 39200147, 2024).
Cognitive impairment (1 paper, 2026). Abnormal cognition is characterized by deficits in thinking, reasoning, or remembering. "For example, BMP4 overexpression in transgenic mice impairs memory and increases Aβ and tau accumulation, whereas lower levels of BMP6 in AD patients are associated with cognitive impairment." (PMID 41480410, 2026).
coronary artery disease (1 paper, 2010). "Increased SPC numbers have also been observed in (non-diabetic) patients with manifest coronary artery disease; however, whether SPC from these patients have altered TGF-β/BMP-6 expression has not been studied." (PMID 20858224, 2010).
dementia (1 paper, 2025). Loss of intellectual abilities interfering with an individual's social and occupational functions. "Our study extends these findings by suggesting a potentially protective effect of BMP6 in specific brain regions associated with AD in older adults without dementia." (PMID 40734820, 2025). "This study examined the association between plasma BMP6 levels and the rates of regional brain atrophy among older adults without dementia." (PMID 40734820, 2025). "In conclusion, our study provides evidence that higher plasma BMP6 levels are associated with a slower rate of volume reduction in the hippocampus, entorhinal cortex, middle temporal cortex, and whole brain among older adults without dementia." (PMID 40734820, 2025). "Plasma BMP6 levels were not correlated with the enlargement of ventricles among older adults without dementia (r = −0.002, p = 0.97)." (PMID 40734820, 2025). "Plasma BMP6 levels were not correlated with volumes of hippocampus among older adults without dementia (r = 0.06, p = 0.25)." (PMID 40734820, 2025). "Plasma BMP6 levels were not correlated with volumes of whole brain among older adults without dementia (r = 0.03, p = 0.57)." (PMID 40734820, 2025). "Plasma BMP6 levels were positively correlated with volumes of entorhinal cortex among older adults without dementia (r = 0.12, p = 0.026)." (PMID 40734820, 2025). "Plasma BMP6 levels were not correlated with volumes of fusiform among older adults without dementia (r = 0.015, p = 0.78)." (PMID 40734820, 2025).
diabetic nephropathy (1 paper, 2017). "It has been reported to decrease fibrosis and glomerulosclerosis in diabetic nephropathy by inhibiting the PPARy/TGF-β pathway and reversing expression of Bmp6 and Mmp1357." (PMID 28051114, 2017).
diffuse large B-cell lymphoma (1 paper, 2005). "In addition, by gene expression profiling, BMP-6 significantly increased the predictive value for a multi-gene signature test and was associated with a poor outcome in diffuse large B cell lymphomas (DLBCL)." (PMID 15877825, 2005).
dwarfism (1 paper, 2022). "These genes were mainly involved in bone resorption (e.g., PTGER4), bone mineralization (e.g., BMP6), and dwarfism (e.g., GDF6 and PTDSS1)." (PMID 34893856, 2022).
enthesitis (1 paper, 2014). Inflammation at the site of insertion of ligaments, tendons, and other fibrous structures into bone. "By immunohistochemistry staining, BMP6 was positive in hypertrophic chondrocyte-like cell showing later stage of endochondral bone formation in ankylosing enthesitis." (PMID 25121767, 2014).
esophageal squamous cell carcinoma (1 paper, 2020). Esophageal squamous cell carcinoma (ESCC) is a type of esophageal carcinoma (EC) that can affect any part of the esophagus, but is usually located in the upper or middle third. "In esophageal squamous cell carcinoma (ESCC), miR-21, miR-130b, and miR-301 downregulate their target mRNAs, which include BMP6, PDCD4, and TIMP4, and induces EMT." (PMID 32967226, 2020).
fibrosis (1 paper, 2023). the formation of excess fibrous connective tissue in an organ or tissue in a reparative or reactive process. "In this study, we focused on the role of BMP6 in myocardial fibrosis during ventricular remodelling following MI." (PMID 37313693, 2023). "Therefore, loss‐of‐function and gain‐of‐function were used to doubly verify that BMP6 inhibited cardiac fibrosis progression and inflammatory infiltration in cardiac fibroblasts after hypoxia in vitro." (PMID 37313693, 2023).
glaucoma (1 paper, 2020). Increased pressure in the eyeball due to obstruction of the outflow of aqueous humor. "Thus the role of other variants in BMP6 or other BMPs in glaucoma cannot be ruled out and needs further investigations." (PMID 32641001, 2020).
Hepatic steatosis (1 paper, 2023). Steatosis is a term used to denote lipid accumulation within hepatocytes. "On the other hand, MC-LR exposure in hepatocytes downregulated several gene expressions, for example, in NAFLD bone morphogenetic protein 6 (BMP6) expression was up-regulated and associated with hepatic steatosis." (PMID 37505679, 2023).
Hodgkins lymphoma (1 paper, 2025). A heterogeneous group of malignant lymphoid neoplasms of B-cell origin characterized histologically by the presence of Hodgkin and Reed-Sternberg (HRS) cells in the vast majority of cases. "Case #3, who had B-ALL, had variants of both the MAP2K2 and BMP6 genes, which were also detected in his brother, who had Hodgkin’s lymphoma." (PMID 40995433, 2025). "The LP MAP2K2 c.907C>T p.R303C and LP BMP6 c.1007G>A p.Gly336Glu variants were detected in B-ALL index case #3 and his brother with Hodgkin’s lymphoma." (PMID 40995433, 2025).
insulinoma (1 paper, 2024). "The effect of BMP6 or 5HT on pancreatic β-cells has been studied in vitro using the INS-1 832/13 rat insulinoma cell line." (PMID 39063084, 2024). "The direct effect of BMP6 and 5HT on pancreatic β-cells was studied using rat insulinoma cell line INS-1 832/13 as a model in vitro." (PMID 39063084, 2024).
iron disorders (1 paper, 2015). "In the present study we investigated the Bmp6 expression in isolated liver cells, in response to physiological iron changes and in murine models of iron disorders." (PMID 25860887, 2015).
iron-refractory iron deficiency anemia (1 paper, 2020). "MT-2 (matriptase-2, TMPRSS6, transmembrane protease serine 6) is ubiquitously expressed in the liver, invalid of MT-2 due to genetic mutation causes iron-refractory iron deficiency anemia (IRIDA), and MT-2 is also downregulated by iron and BMP6." (PMID 32454791, 2020).
ischemia (1 paper, 2022). A hypoperfusion of the BLOOD through an organ or tissue caused by a PATHOLOGIC CONSTRICTION or obstruction of its BLOOD VESSELS, or an absence of BLOOD CIRCULATION. "Here, we hypothesize that, as it occurs in ischemia-induced brain damage, the increase of BMP6 may reduce ischemia/reperfusion injury by inhibiting apoptotic pathways." (PMID 35625854, 2022).
ischemic stroke (1 paper, 2026). A stroke disorder caused by obstruction of blood flow to the brain, due to thrombotic (local blood clot formation) or embolic (due to a blood clot or other material traveling from another site) event. "Recent studies showed that BMP6/Smad activation has been linked to inflammation and ferroptosis in ischemic stroke models." (PMID 41525272, 2026).
joint diseases (1 paper, 2006). "They compared synovium from RA and spondyloarthropathies with synovium from traumatic joint diseases and found BMP-2 and BMP-6 to be expressed most consistently with a calculated relative expression in the range 0.002 to 0.2% compared with β-actin." (PMID 16542506, 2006).
lentivirus infection (1 paper, 2022). Virus diseases caused by the Lentivirus genus. "We established BMP6 knockdown and overexpression cellular models in MCF-7/Adr cells by lentivirus infection." (PMID 36532723, 2022).
liver cirrhosis (1 paper, 2024). "Likewise, liver cirrhosis did not affect plasma BMP6 levels." (PMID 39200147, 2024).
lung adenocarcinoma (1 paper, 2021). A carcinoma that arises from the lung and is characterized by the presence of malignant glandular epithelial cells. "We screened and verified four differentially expressed BMPs (BMP2, BMP5, BMP6, and GDF10) and one BMPR (ACVRL1), which all were downregulated in lung adenocarcinoma tissues." (PMID 34745928, 2021). "BMP2, BMP5, BMP6, GDF10, and ACVRL1 were verified as downregulated in lung adenocarcinoma." (PMID 34745928, 2021).
lymph node metastasis (1 paper, 2012). "Among the significant methylated genes, APC, BMP6, BRCA1 and P16 represented higher methylation proportions in matched lymph node metastasis compared to those of the normal tissue (P < 0.05 and P < 0.01, P < 0.0001, P < 0.05; respectively)." (PMID 22695536, 2012). "The contribution of aberrant methylation alterations of BMP6, BRCA1 and P16 genes in lymph node metastasis might provide a further clue to establish useful biomarkers for screening metastasis." (PMID 22695536, 2012).
medulloblastoma (1 paper, 2021). A malignant, invasive embryonal neoplasm arising from the cerebellum. "We then repeated these experiments in SHH (UW426) and Group 3 (MED8A) medulloblastoma cells and observed that both cell lines responded to FSK/Bmp6/Bmp12 treatment with CREB phosphorylation following serum starvation, albeit at varying rates." (PMID 34373489, 2021).
menopause (1 paper, 2025). Cessation of menstruation, occurring in (e.g.) the human female usually around the age of 50. "Activation of estrogen receptors leads to the expression of osteogenic genes such as bone morphogenetic protein 6 (BMP-6), type I collagen, and osteocalcin, thereby enhancing bone formation and counteracting the detrimental effects of estrogen deficiency typical of menopause." (PMID 41226117, 2025).
Myocardial fibrosis (1 paper, 2023). "To investigate the potential mechanism associated with BMP6 regulation of myocardial fibrosis, we extracted cardiac fibroblasts from lactating mice and transfected them with BMP6 siRNA and scramble siRNA." (PMID 37313693, 2023). "Moreover, knockdown of BMP6 aggravates myocardial fibrosis after MI mainly through upregulating the expression of AP‐1/CEMIP." (PMID 37313693, 2023). "Besides, a knockout of BMP6 reduced myocardial fibrosis, which was in line with the results reported." (PMID 37313693, 2023). "Therefore, we speculate that CEMIP may represent a potential mechanism through which silencing BMP6 expression can aggravate myocardial fibrosis." (PMID 37313693, 2023). "Consequently, it is reasonable to suspect that BMP6 inhibited CEMIP expression by suppressing AP‐1 transcriptional activity, thereby slowing the progression of myocardial fibrosis after MI." (PMID 37313693, 2023).
nephrocalcinosis (1 paper, 2012). Nephrocalcinosis is a disorder that occurs when too much calcium is deposited in the kidneys. "In light of these previous results, the data from the current study suggest a mechanism in which the upregulation of Bmp6 induces the differentiation of osteoblast-like cells in the kidney, resulting in the progression of nephrocalcinosis." (PMID 22235299, 2012).
osteosclerosis (1 paper, 2022). Abnormally high bone density. "Mature osteoclasts can reduce the Wnt signaling pathway inhibitor osteosclerosis protein expression and through the secretion of Wnt10b and BMP6 promoting osteoclast areas of osteoblast differentiation and bone formation." (PMID 35794997, 2022).
parasitemia (1 paper, 2017). "However, we found that hepatic Bmp6 mRNA was downregulated as parasitemia increased." (PMID 28893916, 2017).
Pectus excavatum (1 paper, 2015). A defect of the chest wall characterized by a depression of the sternum, giving the chest ("pectus") a caved-in ("excavatum") appearance. "Thus, deletion of the BMP6 gene could be the potential cause of pectus excavatum that was observed in four of the five individuals with the 6p25.1p24.3 deletions." (PMID 26174853, 2015).
promyelocytic leukemia (1 paper, 2023). "These proteins have been also described to regulate differentiation of human promyelocytic leukemia cells and BMP6 promoter methylation is likely to be a common epigenetic event at later stages of adult T-cell leukemia." (PMID 37550636, 2023).
prostate tumor (1 paper, 2013). "Furthermore, it has been shown that BMP6 secreted from prostate tumor cells acts directly upon macrophages to stimulate secretion of IL-6, which ultimately results in neuroendocrine differentiation of the tumor." (PMID 23840733, 2013).
pterygium (1 paper, 2021). A wedge-shaped fibrovascular lesion arising from the bulbar conjunctiva and extending to the cornea. "An increase in EMT in corneal epithelium in pterygium is also suggested, regulated by KLF7, BMP2, BMP6, and SNAI1." (PMID 34769520, 2021). "Elevated expression of BMP6 was previously shown in pterygium We observed modest upregulation of BMP2 in both pterygium subtypes, but BMP6 was upregulated only in pterygium-NE." (PMID 34769520, 2021). "Our further analysis of pathways controlled by upstream regulator TP63 suggested increased EMT in pterygium, regulated by BMP2, BMP6, SNAI1 and KLF7." (PMID 34769520, 2021).
sarcoma (1 paper, 2022). A usually aggressive malignant neoplasm of the soft tissue or bone. "Remarkably, and in cancer, high levels of RNF4 and BMP6 were associated with poor prognosis and shorter disease-free survival in multiple sarcoma types." (PMID 36153321, 2022). "RNF4 and BMP6 mRNA and protein levels are highly elevated in multiple types of human sarcomas and are associated with poor prognosis and reduced patient survival." (PMID 36153321, 2022). "However, given the role of BMP6 and RGMb as survival factors in sarcoma, these experiments should also address a potential transformation/tumor-promoting aspect of these factors, as they may be a “double adage sord”." (PMID 36153321, 2022). "Thus, suggesting that the pro-tumorigenic activity of RNF4 is multifaceted and that the RNF4-RGMb-BMP6 pathway acts primarily as a pro-survival pathway in sarcomas and therapy-resistant cells, and that BMP6 and RGMb inhibition has a potent anti-cancer activity." (PMID 36153321, 2022). "We, therefore, tested patient-derived sarcoma tissue microarray (TMA) for the protein levels of RNF4 and BMP6 and RGMb." (PMID 36153321, 2022).
sialadenitis (1 paper, 2020). Sialadenitis is an infection of the salivary glands. "The relationship between minor SG BMP6 expression and two important SG-related manifestations of pSS, SG dysfunction assessed by unstimulated whole saliva (UWS) flow rate and sialadenitis assessed by focus score (FS) or lymphocyte infiltration area was determined." (PMID 32076051, 2020).
synovial sarcoma (1 paper, 2020). "The six unshared genes (CEBPB, BMP6, PTGS2, DMP1, FGF2, and H2AFV) are likely the important contributors to the ossifying phenotype seen in the metastatic synovial sarcomas." (PMID 32290096, 2020).
type 2 diabetes (1 paper, 2022). "Recently, BMP6 has been shown to play a novel role in glucose homeostasis in type 2 diabetes mice, and treatment with BMP6 for six days resulted in improved glucose tolerance via regulation of hepatic glucose output in ob/ob mice." (PMID 35954181, 2022).
Type I diabetes (1 paper, 2010). "We hypothesized that inducing Type I diabetes in mice enhances SPC differentiation and numeric outgrowth with decreased BMP-6 expression and increased TGF-β expression in diabetic SPC." (PMID 20858224, 2010).